CRP (C-reactive protein)
Diseases named in the same sentence as CRP in open-access papers (continued):
Sharing a sentence is not in itself a finding about the gene and the disease.
Anxiety (continued). "Elevated maternal IL-6 or CRP (C-reactive protein) levels (markers of inflammation, often associated with antennal depression and anxiety) during pregnancy have been linked with adverse pregnancy and birth outcomes and with new-born functional and structural brain alterations." (PMID 32408643, 2020). "The hypothesis of the association of anxiety with systemic inflammation corroborates a recent finding, showing an association of the inflammation marker C-reactive protein (CRP), with increased risk of suicide in patients with anxiety disorders." (PMID 32640734, 2020). "Additionally sleep disturbance was associated with anxiety, enthesitis, levels of C-reactive protein and erythrocyte sedimentation rate." (PMID 27327082, 2016). "The findings showed that CRP levels were significantly elevated in treatment-resistant patients even after adjusting for BMI, and higher CRP was associated with specific symptoms such as vegetative depressive symptoms, anxiety, higher BMI, and childhood adversity." (PMID 40943152, 2025). "Furthermore, 37 (57%) patients presented with anxiety, and only mechanicalventilation and IL-33 and CRP levels were significantly associated with this outcomein the univariate analysis.However, none of the variables were independently associated with anxiety in thissample." (PMID 37712803, 2023). "For anxiety, an increased frequency of having trouble relaxing during anxiety episodes and experiencing muscle symptoms was associated with an increase in reported chronic pain, and there was an important interaction between informing a professional about anxiety and CRP in predicting pain." (PMID 37865679, 2023). "In examining whether the mean level of CRP at ages 9 and 15 years mediated the association between persistent anxiety and PEs at age 24, path analysis model fit indices indicated good model fit (χ2 = 3.26, p = 0.66, root mean square error of approximation 0, comparative fit index 1.00)." (PMID 35151465, 2022). "Therefore, evidence exists of an association of CRP with both anxiety and psychotic outcomes." (PMID 35151465, 2022). "This suggests that the association between CRP and fatigue might have been confounded by anxiety." (PMID 26599129, 2015). "Significant predictors included educational level, sleep disorders, anxiety, Revised Amyotrophic Lateral Sclerosis Functional Rating Scale total scores, C-reactive protein levels, and the Systemic Inflammation Response Index." (PMID 41018179, 2025). "Significant reductions were observed in anxiety levels, systolic blood pressure, heart rate, and serum C-reactive protein levels in the music intervention group compared to the control group." (PMID 40347423, 2025). "Observed indicators included vital sign stability, pain and anxiety scores, serum biochemical markers (serum amylase, C-reactive protein [CRP], and white blood cell count), complication rates, and nursing satisfaction." (PMID 40324238, 2025). "C-reactive protein (CRP) is an inflammatory protein which, along with pro-inflammatory cytokines, has been associated with immune-mediated depression and anxiety." (PMID 40823322, 2025). "The gold-standard C-reactive protein (CRP) requires venipuncture, which, despite providing high-quality samples, can cause discomfort, anxiety, and pain, particularly in vulnerable populations such as older patients." (PMID 40856619, 2025). "Our analysis identified GAD7−6 (“Irritability”) as a bridge symptom connecting the anxiety–depressive–CRP network." (PMID 41048872, 2025). "The relationship between Children’s dietary inflammatory index and anxiety wasmediated by C-reactive protein and waist circumference." (PMID 40110388, 2025). "It has been evidenced that HDL-C improves vascular health by lowering inflammatory markers such as CRP, which consequently helps alleviate anxiety." (PMID 41144483, 2025).
Anxiety (continued). "In a study on Australianadolescents, the western diet pattern (i.e., high amounts of red meat, processedand refined foods, sweets, etc.)was found to be associated with higher BMI,waist circumference, depressive and anxiety symptoms, and CRP and leptin levels." (PMID 40110388, 2025). "Anxiety and sleep disturbances were also evaluated and inflammatory status was determined based on CRP levels." (PMID 41470126, 2025). "Prior research in population-based cohorts have found CRP to be associated with an increased risk for anxiety disorders, although results are inconsistent and other studies indicate that anxiety prospectively predicts an increase in circulating CRP levels." (PMID 40348744, 2025). "Our study identified several key factors associated with heightened anxiety symptoms in TBI patients: younger age, underlaying disease, TBI classification, delirium, elevated CRP levels, diminished self-efficacy, and insomnia." (PMID 39554848, 2024). "The GEE analysis revealed that delirium, CRP levels, self-efficacy, underlying diseases, insomnia, TBI classification, age, and sleep duration were associated with anxiety symptoms in TBI patients at 6 months post-discharge (P < 0.05)." (PMID 39554848, 2024). "Prior research in population-based cohorts have found CRP to associated with an increased risk for anxiety disorders, although results are inconsistent and other studies indicate that anxiety prospectively predicts an increase in circulating CRP levels." (PMID 38699368, 2024). "Inflammatory biomarkers including cytokines and C-reactive protein have shown to positively correlate with anxiety symptoms and negatively correlate to functional connectivity between the lower amygdala and ventromedial PFC in women with anxiety and PTSD." (PMID 38903645, 2024). "For objective 2, frequency of sexual abuse and informing a professional about anxiety significantly interacted to predict elevated CRP." (PMID 37865679, 2023). "A total of seven significant mtDNA × CRP interactions were found for anxiety, such as m.3915G>A(MT-ND1) for self-reported anxiety in total subjects (P = 6.59 × 10−3), m.4561T>C(MT-ND2) (P = 3.04 × 10−3) for GAD-7 score in total subjects." (PMID 37344456, 2023). "In the cohort as a whole, higher CRP concentrations correlated with elevated anxiety as assessed by the GAD-7 scale." (PMID 37107316, 2023). "The purpose of the current analysis was to examine the relationships between reported ACE(s), anxiety, and levels of CRP in adults with chronic pain." (PMID 37865679, 2023). "The prevalence and severity of anxiety were significantly associated with PCT, IL-6, and CRP (p<0.05)." (PMID 37621784, 2023). "For example, m.12633C>A (MT-ND5) was identified to interact with CRP for both in male subjects with self-reported anxiety (P value = 4.90 × 10−3) and all subjects with PHQ-9 score (P value = 9.17 × 10−4)." (PMID 37344456, 2023). "For participants with CRP data who met the inclusion criteria (n = 2007), similar models were run between ACEs, anxiety, and CRP, and CRP and chronic pain." (PMID 37865679, 2023). "Of note, there was an important interaction between informing a professional about anxiety and CRP in predicting pain." (PMID 37865679, 2023). "One study revealed an inverse relationship between CRP and fibrinogen levels and symptoms of anxiety in healthy women." (PMID 37840785, 2023). "As a result of the rapid rise of CRP level in inflammatory conditions, CRP is considered as an important protein involved in the acute phase of inflammation by playing a significant role in mental stress, anxiety, neoplastic disease and myocardial infarction." (PMID 35228564, 2022). "Overall, the current results suggest that subtypes of anxiety and depressive symptomatologies differ based on the general inflammatory marker CRP." (PMID 35361785, 2022).
Anxiety (continued). "The HAMD score (p = 0.031), anxiety/somatization factor score (p = 0.015), and sleep disorder (p = 0.029) of TRD patients were positively associated with hs-CRP level, while the onset age (p = 0.009) was negatively correlated with the hs-CRP level." (PMID 35163538, 2022). "Further, there is some indication of association between anxiety and higher CRP levels, with previous evidence reporting that anxiety symptoms alone increase the probability for elevated CRP levels." (PMID 35151465, 2022). "In a recent study, CRP level was negatively correlated with amygdala–ventromedial prefrontal cortex connectivity in depressed patients with high levels of inflammation and anxiety symptoms." (PMID 36295080, 2022). "Using CRP as a continuous variable, the adjusted OR for higher anxiety symptom score per-unit increase in log CRP was 1·03 (95% CI, 1·02–1·05)." (PMID 34505025, 2021). "Compared to placebo, 7-day atorvastatin increased the recognition (p = 0.006), discriminability (p = 0.03) and misclassifications (p = 0.04) of fearful facial expression, independently from subjective states of mood and anxiety, and C-reactive protein levels." (PMID 34872404, 2021). "By comparison, we found that patients with anxiety symptoms had elevated serum vitamin A, glycated serum protein, CRP, and aspartate aminotransferase as well as decreased serum total protein and albumin." (PMID 34007268, 2021). "Further support is derived from CRP’s positive linear relationship with anxiety scores, even in adjusted models." (PMID 33301421, 2021). "The correlation between the hs-CRP level and postoperative anxiety reached a near significance (p = 0.081)." (PMID 34943627, 2021). "Using CRP as a categorical variable, the adjusted OR for higher anxiety symptom score for participants in the top, compared with bottom, quintile of CRP was 1·12 (95% CI, 1·05–1·19)." (PMID 34505025, 2021). "Furthermore, we have carried out one- and two-sample MR analyses to test whether associations of IL-6 and CRP with specific depressive and anxiety symptoms are likely to be causal using genetic variants regulating levels/activity of these inflammatory markers as instrumental variables." (PMID 34135474, 2021). "These previous studies indicate that mindfulness acts on different physiological markers related to anxiety by reducing cortisol, C-reactive protein (CRP), blood pressure, heart rate, triglycerides and tumour necrosis factor alpha (TNF-α)." (PMID 32260096, 2020). "After social isolation, inpatients with schizophrenia showed higher levels of CRP and psychological stress, more severe anxiety, and worse sleep quality." (PMID 33235185, 2020). "In a national database with 2861 participants, higher C reactive protein (CRP) levels were similarly associated with somatic and cognitive symptoms of anxiety in male subjects, while IL-6 and TNF-a levels were associated with somatic symptoms of anxiety." (PMID 32824625, 2020). "One subject was clearly different with lower fitness, higher levels of stress and anxiety, and somatic signs as back pain, peak in masseter tone, increased blood cortisol and C-reactive protein." (PMID 31164833, 2019). "Clinical phenotypes most strongly associated with CRP and heavily weighted on the first PLS component were vegetative depressive symptoms, BMI, state anxiety and feeling unloved as a child or wishing for a different childhood." (PMID 29764522, 2019). "We also found evidence that state anxiety was related with CRP, which is compatible with prior data linking acute endotoxin exposure to anxious and depressive states in healthy volunteers." (PMID 29764522, 2019). "Physical functioning, fatigue, fear/anxiety, social role satisfaction, and CRP levels improved following participation in this exercise intervention." (PMID 29789774, 2018). "The secondary endpoints comprise respiration rate, 6MWT, panic attack rates, and the CRP concentration, which will be evaluated before and 6 and 12 months after treatment." (PMID 28303154, 2017).
Anxiety (continued). "The abnormality rates of IL-6, IL-8, TNF-α and CRP in both the BD group and the atypical BD group were all significantly higher than those in the simple anxiety group (P < 0.05)." (PMID 29065864, 2017). "Our findings showed that the effects of the MBP on test anxiety were comparable to those of the CRP." (PMID 27764151, 2016). "Other investigators have reported associations between inflammation (defined by increased levels of cytokines and CRP) and neuropsychiatric disease, such as major depressive disease, generalised anxiety disorder, or even anxiety in healthy adults." (PMID 26788321, 2015). "CRP level andC-DII score explained 20.4% (R2) of the change in anxiety." (PMID 40110388, 2025). "The elevated CRP and GlycA in anxious individuals within this work may reflect a role of inflammatory processes in mediating anxiety symptoms." (PMID 40485662, 2025). "Regarding the association between anxiety and CRP levels, there have not been any reported correlations." (PMID 40095803, 2025). "Notably, while the effect of CRP on pain was smaller than that of anxiety in this samples (β = .12 vs. β = .20), it remained a statistically significant and independent predictor of pain symptoms." (PMID 40823322, 2025). "PsA patients with anxiety also had slightly higher CRP levels at baseline." (PMID 39504461, 2025). "Insomnia and anxiety symptoms may represent possible targets for personalised treatment with immunomodulatory agents in people with elevated CRP." (PMID 39359158, 2024). "We measured CRP at a single time point, but its link to anxiety may reflect an early inflammatory surge that increases the risk of subsequent psychological issues." (PMID 39554848, 2024). "After excluding pwALS who had a CRP level above 10 mg/L around the time of immune cell measurement, we observed similar results, although statistically significant result was only noted for anxiety." (PMID 39650285, 2024). "Using HADS-A scores as the dependent variable, the GEE analysis revealed that delirium, CRP levels, self-efficacy, underlaying disease, insomnias, TBI classification, age, and sleep duration were significant factors influencing anxiety in traumatic brain injury patients post-discharge (P < 0.05)." (PMID 39554848, 2024). "Some studies noted a relationship between anxiety symptoms and the CRP level." (PMID 36525411, 2022). "In mice stressed by immobilization, decreased locomotor activity, anxiety-like behavior, and contact with other individuals were observed, as well as increased oxidative stress and increased levels of nitric oxide in the brain and plasma C-reactive protein." (PMID 35795852, 2022). "The relevant biomarkers assessed in the anxiety study population were CRP and IL-1β." (PMID 35053845, 2022). "We detected 16 CRP × gut microbiome interaction with suggestive significance for anxiety GAD-7 score, like O_Bacteroidales (β = 0.010, P = 4.00 × 10–4), O_Selenomonadales (β = − 0.010, P = 1.20 × 10–3), O_Clostridiales (β = 0.009, P = 2.70 × 10–3) and G_Holdemanella (β = − 0.008, P = 4.20 × 10–3)." (PMID 34481527, 2021). "Cohort studies of affective symptoms also suggest that circulating IL-6 and CRP concentrations are predominantly associated with depressive rather than anxiety symptoms." (PMID 34505025, 2021). "Overall, we observed that 7-day atorvastatin treatment, compared to placebo, led to increased recognition, sensitivity and misclassifications for fearful facial expressions, but not for other emotions, independently from subjective states of mood and anxiety, and C-reactive protein levels." (PMID 34872404, 2021). "In depressed patients, CRP has been shown to negatively correlate with the functional connectivity of both the striatum and amygdala to mPFC, which mediate specific depressive features of anhedonia and anxiety, respectively." (PMID 34535766, 2021). "Additionally, there was a positive correlation between salivary CRP and anxiety scores (r = .664; p = .026)." (PMID 31822925, 2020).
Anxiety (continued). "We used the multivariate technique of partial least squares (PLS) to explore the relationships between CRP and multiple clinical phenotypes – ranging from body mass index (BMI) to questionnaire items for depressive symptoms, anxiety states or history of childhood adversity." (PMID 29764522, 2019). "Secondary outcomes include measures of resilience, rumination, anxiety, psychological distress, well-being, salivary cortisol, plasma levels of C-reactive protein, smoking and alcohol use, weight gain, sleep problems, health-related quality of life, health resource utilisation and productivity." (PMID 30598484, 2018). "Finally, as basal levels of CRP, IL-6 and TNF-α areavailable, we are able to compare associations of basal versus LPS-stimulatedcytokine levels with depression and anxiety within the same study sample (fourthaim)." (PMID 27244234, 2016). "Basal CRP, IL-6 andTNF-α, as well as most individual LPS-stimulated inflammation markers (IL-6,IL-8, IL-10, IL-18, MCP-1, MIP-1α, MIP-1β, MMP2 and TNF-β) weresignificantly associated with depressive and anxiety symptom severity." (PMID 27244234, 2016). "In this context, we speculated that decentering components of the MBP and CRP might contribute to reduce test anxiety." (PMID 27764151, 2016). "This hypothesis is supported by our findings of a higher correlation coefficient between CRP levels and fatigue scores after patients with high anxiety scores were excluded." (PMID 26599129, 2015). "Similarly, higher scores on the Spielberger State-Trait Anxiety Inventory were significantly correlated with elevated C-reactive protein, interleukin-6 and fibrinogen levels in 853 middle-aged adults." (PMID 22808180, 2012). "There was a non-significant CRP-anxiety association using MR (β = 0.12; p = 0.054)." (PMID 40348744, 2025). "Moreover, in a double-blind randomized placebo-controlled trial, an ashwagandha extract administered at a dosage of 125 mg/day significantly decreased the modified anxiety Hamilton scale (mHAM-A), the plasma biomarkers cortisol and CRP, blood pressure, and heart rate." (PMID 40226680, 2024). "However, those reporting myalgia, low mood, and anxiety at follow‐up had lower admission levels of IL‐6 (34.9 vs. 52.0 pg/mL, p = .043), CRP (83 vs. 105 mg/L, p = .048), and ferritin (357 vs. 568 ug/L, p = .01) respectively, compared with those who did not report these symptoms." (PMID 37904690, 2023). "In conclusion, our results support the hypothesis that some anxiety and stress-related disorders (including panic disorder, stress/adjustment disorders and GAD) may be associated with high levels of inflammation, as measured by CRP." (PMID 35028602, 2022). "However, in the regression models, the association between ACEs and anxiety, and CRP and loneliness did not remain." (PMID 36198766, 2022). "Results for sex-stratified MR analyses suggested that higher IL-6 could be a risk factor for depressive symptoms specifically for women while higher CRP could be protective for depressive symptoms specifically for men and for anxiety symptoms specifically for women." (PMID 34505025, 2021). "However, we did not observe significant associations between CRP and scores on questionnaire measures of depressive symptom severity, anxiety, anhedonia or fatigue in this group of depressed cases." (PMID 34535766, 2021). "Although our study revealed that the percentage of Treg cells and serum levels of CRP and INF-γ differ significantly between infected and uninfected patients on day 3, we cannot fully exclude the influence of hospital admission-associated anxiety and stress on the systemic immune system." (PMID 27682880, 2017). "The severity of the physio-affective phenome (CFS, depressive and anxiety dimensions), which represents a major dimension of Long COVID, is significantly predicted by increased IgM/IgA-synapsin, IgA/IgG-MBP, IgG-MOG, and CRP and AOPP levels." (PMID 39522688, 2025).